FZD9 (frizzled class receptor 9)
Diseases named in the same sentence as FZD9 in open-access papers (continued):
Sharing a sentence is not in itself a finding about the gene and the disease.
meningioma (2 papers, 2017 to 2018). A generally slow growing tumor attached to the dura mater. "For highly significant grade-related differential markers, single positive staining of FZD9+ or GFAP+ was statistically significantly higher in grade II/III meningiomas (Brown–Forsythe ANOVA, P < 0.01)." (PMID 29849507, 2018). "For double-staining analysis, the most significant average count increase in grade II/III meningiomas was seen for Vimentin+FZD9+ (Brown–Forsythe ANOVA, P < 0.01)." (PMID 29849507, 2018). "Regions that were significantly frequently occurring in grade II/III but never in grade I meningiomas included those that were positive for CD133+SOX2±Vimentin+FZD9+GFAP+BTIII+SSEA4+Olig2+, and Nestin+Ki67+CD133+Vimentin+FZD9+GFAP+BTIII+SSEA4+Olig2+." (PMID 29849507, 2018). "Cells positive for SSEA4 and OLIG2 were more frequent in grade II/III meningiomas and the number of FZD9-positive cells was significantly higher in grade II/III meningiomas, although the overall levels remained relatively low, implying that growth of FZD9-positive cells in meningiomas is restricted." (PMID 29849507, 2018). "The correlation of FZD9 with SOX2 is perhaps not surprising, giving that they are both part of the WNT signaling pathway, a pathway that is activated in some meningiomas." (PMID 29849507, 2018).
acute lymphoblastic leukemia (1 paper, 2022). Leukemia with an acute onset, characterized by the presence of lymphoblasts in the bone marrow and the peripheral blood. "FZD7 and FZD8 are expressed in most acute lymphoblastic leukemia (ALL) cells, while FZD3, FZD4, and FZD9 are occasionally detected." (PMID 36452482, 2022).
acute myeloid leukemia (1 paper, 2016). Acute myeloid leukemia (AML) is a group of neoplasms arising from precursor cells committed to the myeloid cell-line differentiation. "Hypermethylation of FZD9 correlates with transcriptional repression and is an independent predictor of poor prognosis for patients with acute myeloid leukemia (AML)." (PMID 26884818, 2016).
autism spectrum disorder (1 paper, 2012). A spectrum of developmental disorders that includes autism, and Asperger syndrome. "Microdeletion and microduplication copy number variations are found in patients with autism spectrum disorder and in a number of cases they include genes that are involved in the canonical Wnt signaling pathway (for example, FZD9, BCL9 or CDH8)." (PMID 23083465, 2012).
basal cell carcinoma (1 paper, 2020). A carcinoma involving the basal cells. "Indeed, the genes driving the basal cell carcinoma pathway are FZD9, FZD7, FZD2, DVL1, and AXIN1, all playing a role in the Wnt signaling pathway, which has already been linked to AD and PD." (PMID 33362460, 2020).
bone sarcoma (1 paper, 2015). A sarcoma that arises from the bone. "We found that FZD3, FZD5, FZD9 and FZD10 were prominently expressed in all bone sarcoma cells as compared to hMSC." (PMID 25999350, 2015).
Cushing syndrome (1 paper, 2021). Cushing's syndrome (CS) encompasses a group of hormonal disorders caused by prolonged and high exposure levels to glucocorticoids that can be of either endogenous (adrenal cortex production) or exogenous (iatrogenic) origin. "For example, WNT11, WNT9A, and FZD9 were all enriched in cancer signaling pathways, the Cushing syndrome signaling pathway, and the Wnt signaling pathway." (PMID 34737761, 2021).
cutaneous melanoma (1 paper, 2020). A primary melanoma arising from atypical melanocytes in the skin. "When comparing our signature genes with the TCGA expression data, the FZD9 transcript showed a higher mean expression value in primary cutaneous melanoma samples in relation to metastatic samples." (PMID 32431053, 2020).
inflammatory bowel disease (1 paper, 2015). A spectrum of small and large bowel inflammatory diseases of unknown etiology. "In our study, the binding specificity of Frizzled 9 with Wnt3a was demonstrated in ENS compartment and suggested the involvement of FZD9 in neuronal response to inflammation in light of the evidence that a significant increase of Wnt3a and FZD9 is observed in inflammatory bowel diseases." (PMID 25644719, 2015).
insulinomas (1 paper, 2021). "Since Fzd9 deficiency blocks the appearance of Myc-driven hyperplastic insulinomas, we next investigated the possibility that MycER is simply no longer functional in tamoxifen-treated Fzd9KO/KO;MycER;BclXL islets." (PMID 33653688, 2021). "Here, we demonstrate for the first time the key role of the Wnt receptor Fzd9 and Wnt signaling in Myc-induced insulinomas." (PMID 33653688, 2021). "We show that Fzd9 does, indeed, play a critical function in the development of Myc-driven insulinomas." (PMID 33653688, 2021).
leukemia (1 paper, 2025). A malignant (clonal) hematologic disorder, involving hematopoietic stem cells and characterized by the presence of primitive or atypical myeloid or lymphoid cells in the bone marrow and the blood. "Hypermethylation of FZD promoter regions is associated with silencing in certain cancers, as seen with FZD9 in leukemia, leading to impaired Wnt signaling." (PMID 40376615, 2025). "Loss-of-function mutations, such as those affecting FZD9, are linked to conditions like leukemia, where reduced Wnt signaling impairs normal cellular processes." (PMID 40376615, 2025).
lung adenoma (1 paper, 2022). A benign, well circumscribed epithelial neoplasm that arises from the bronchus or the lung parenchyma. "Together, these data suggest the environment in FZD9-/- lungs has altered gene expression and downstream activity that may support development of lung adenomas, but that loss of Fzd9 expression alone does not increase β-catenin activity." (PMID 35924166, 2022).
myeloid malignancies (1 paper, 2009). "As well as genes predominantly methylated in certain HN subtypes, we also identified six genes, i.e. DBC1, DIO3, FZD9, HS3ST2, MOS and MYOD1, that were significantly hypermethylated in B-cell, T-cell and myeloid malignancies." (PMID 19750229, 2009). "As well as identifying genes showing aberrant DNA methylation in certain HN subtypes, we also detected six genes—DBC1, DIO3, FZD9, HS3ST2, MOS, and MYOD1—that were significantly hypermethylated in B-cell, T-cell, and myeloid malignancies." (PMID 19750229, 2009).
Osteopenia (1 paper, 2013). Osteopenia is a term to define bone density that is not normal but also not as low as osteoporosis. "Supporting the relevance of Fzd9 in bone remodeling, it was recently demonstrated that the absence of Fzd9 in mice resulted in osteopenia caused by an autonomous osteoblast defect." (PMID 24391920, 2013). "It was previously demonstrated, that bone marrow stromal cells derived from Fzd9-knockout mice exhibited a diminished capacity to proliferate and form mineralized matrix, suggesting that an intrinsic osteoblast defect may be responsible for the osteopenia observed in these mice." (PMID 24391920, 2013).
tumor (27 papers, 2010 to 2026). "Loss of FZD9 increased tumor multiplicity in vivo with carcinogen exposure, however, this trend was not significant (p=0.08), which reduces the impact of this data." (PMID 35924166, 2022). "Associations of the expression of c-Fos, Wnt2, and Fzd9 with tumor clinical stages." (PMID 28665975, 2017). "FZD9 loss in combination with a carcinogen exposure could augment tumor promotion." (PMID 35924166, 2022). "Genes implicated in cell proliferation and migration such as Tgfβ3, Fzd2, Fzd9, and Lpar3 showed marked downregulation in tumor tissues post-FAA treatment." (PMID 38613073, 2024). "FZD1/2/3/4/5/7/8 expression was significantly higher in tumor tissues than in normal brain tissues; however, FZD9 and FZD10 expression was higher in normal tissues." (PMID 36699699, 2022). "WNT7a binds to FZD9 and signals to peroxisome proliferator activated receptor gamma (PPARγ) through an Erk5-dependent cascade, leading to anti-tumor signaling, including increasing epithelial and reducing mesenchymal gene expression." (PMID 35924166, 2022). "One of these candidate tumor maintenance genes was Fzd9, a member of the “frizzled” gene family of Wnt receptors." (PMID 33653688, 2021). "WNT2 can activate both canonical and non-canonical WNT signalling, while FZD5 and FZD9, both of which are expressed in the high-amplified tumours, activate different branches of the pathway (FZD5 the canonical pathway and FZD9 the non-canonical pathway)." (PMID 34003256, 2021). "In contrast, Fzd9 has anti-tumor function through activation of the PPARγ pathway in the lung, which prevents development of early lesions, and is required for activity of the chemoprevention drug iloprost." (PMID 34604862, 2021). "Studies of Fzd9 function show it to be upregulated in triple-negative breast cancer, but it is also tumor-suppressive in NSCLC." (PMID 34671643, 2021). "In AJ mice, Fzd9 expression decreased in urethane induced tumor tissue compared to uninvolved matched lung tissue." (PMID 27339092, 2016). "Fzd9 is a G-protein coupled transmembrane receptor that is required for the tumor suppressive activity of the Wnt7a signaling pathway in the lung." (PMID 27339092, 2016). "Seventy-five percent (13/17 pairs) of patient samples had higher Fzd9 expression in uninvolved lung tissue compared to tumor tissue." (PMID 27339092, 2016). "We are interested in the role of non-canonical Wnt signaling in non-small lung cancer (NSCLC), specifically the tumor suppressive activities of Wnt7a and its receptor Frizzled 9 (Fzd9)." (PMID 22403725, 2012). "Among these genes, FZD9 is a receptor of Wnt and a putative tumor suppressor gene located on chromosome 7." (PMID 21293051, 2010). "In both lung epithelial and tumor cell lines, miR-520a-5p represses activity of the FZD9 3’UTR." (PMID 35149732, 2022). "In contrast, in the lung FZD9 interacts with WNT7a to activate tumor suppressive signaling." (PMID 35924166, 2022). "Fzd9 was significantly induced within 4 h of acute Myc activation in vivo, its expression was maintained as long as Myc activity was sustained, and rapidly decreased following Myc deactivation and tumor regression." (PMID 33653688, 2021). "However, as Fzd9 has also shown some tumor suppressor activity in acute myeloid leukemia and non-small cell lung cancer, its role in tumorigenesis is still controversial." (PMID 33653688, 2021). "A possible explanation is that FZD9 may be a tumor suppressor in the presence of Wnt ligands in different kinds of cancer." (PMID 32431053, 2020). "The expression of Wnt2 and Fzd9 was also correlated with the tumor stages." (PMID 28665975, 2017).
tumor (continued). "Interestingly, knockdown of hsa-miR29b was enough to abrogate the tumor suppressive effects of Wnt7a and Fzd9 expression in NSCLC cells, suggesting that Wnt7a and/or hsa-miR29b plays a critical during lung tumorigenesis." (PMID 23862015, 2013). "FZD9 in the lung epithelium does not activate canonical β-catenin signaling, but pro-tumorigenic β-catenin activation may be a contributor to the tumor supportive conditions that accompany FZD9 loss." (PMID 35924166, 2022). "Fzd1, Fzd2, Fzd6, Fzd9, and Fzd10 currently do not have any circRNA molecules associated with regulation of their expression, despite their obvious role in cancer signaling and tumor progression, highlighting the potential for future research." (PMID 34671643, 2021). "FZD9 is required in lung epithelial cells for iloprost to activate peroxisome proliferator activated receptor gamma (PPARG) and related anti-tumor signaling." (PMID 35149732, 2022). "Similar to activation by FZD9, PPARG is also activated by prostacyclin in lung epithelial cells, leading to anti-tumor signaling." (PMID 35149732, 2022). "FZD9 interacts with several WNT ligands including WNT2, WNT5a, and WNT3a depending on the tumor; these interactions promote EMT and invasiveness." (PMID 34604862, 2021). "In this report, we presented powerful evidences that high expression of c-Fos, Wnt2 and Fzd9 was found in human OS tissues and MG63 cells, and the level of c-Fos, Wnt2 and Fzd9 expression was correlated with tumor stages." (PMID 28665975, 2017). "In this study, we measured Fzd9 expression in human normal and tumor lung tissues, dysplastic cell lines, and Human Bronchial Epithelial Cells (HBEC) and examined the effects of cigarette smoke and iloprost on Fzd9 expression." (PMID 27339092, 2016). "Because SETDB2 knockdown led to significant inhibition of cell growth, migration and invasion, we further selected six tumor- or differentiation-related genes (WWOX, CADM1/TSLC1, CCDC80, NDRG1, CA9 and FZD9) that have been reported to show altered expression in several cancers including GCs." (PMID 27572307, 2016). "Prostacyclin reduces tumor burden in vivo without the presence of its traditional receptor, suggesting that Fzd9 may be an alternative receptor for prostacyclin in the lung epithelium." (PMID 34604862, 2021).
cancer (20 papers, 2008 to 2025). A tumor composed of atypical neoplastic, often pleomorphic cells that invade other tissues. "One notable characteristic of the carcinoma tumors was high expression of Wnt2b and Fzd9, which cause distinct activation of the canonical pathway, leading to increased transcription." (PMID 18811984, 2008). "FZD9 may have a role in the development of early lung lesions and loss of FZD9 could lead to early lesions more likely to progress to carcinoma through several associated mechanisms." (PMID 35924166, 2022). "Hypermethylation of Wnt signaling in general has been implicated in a variety of cancers, including hypermethylation of WNT9A and FZD9 genes." (PMID 40188944, 2025). "FZD9 also plays a key role in the activity of iloprost, where it is required for iloprost’s activation of PPARγ and downstream anti-cancer signaling." (PMID 35924166, 2022). "FZD9 is also positively regulated in several types of cancer and its inhibition leads to a decrease in cell proliferation and motility." (PMID 36078126, 2022). "Fzd9 is up-regulated in several types of human cancers including human gastric cancer, osteosarcoma and astrocytoma." (PMID 33653688, 2021). "While lncRNA regulation has yet to be described for both Fzd9 and Fzd10, the potential for investigation is clear as they have been shown to be differentially expressed during tumorigenesis in various cancers." (PMID 34671643, 2021). "It has been reported that the direct interaction of WNT7a ligand and its receptor FZD9 repressed cell growth and promoted cell differentiation in NSCLC, indicating an antitumor effect of WNT7a and FZD9 in human cancers." (PMID 29789460, 2018). "Wnt7a is frequently lost in a subset of NSCLC, and restoration of Wnt7a expression in the context of Fzd9 results in increased differentiation and decreased transformed phenotype in cancer cell lines." (PMID 23862015, 2013). "Our results show that miR-520a-5p targets FZD9, identifying a new method of FZD9 regulation induced by cigarette smoke that could impact iloprost’s activation of anti-cancer signaling pathways." (PMID 35149732, 2022). "However, knowledge of miRNA regulation of Fzd9 is limited, with only one published study showing miR-31 indirectly inhibiting Fzd9 expression and supporting cancer-promoting signaling in NSCLC in vitro and in vivo." (PMID 34671643, 2021). "In Proteoglycans in cancer pathway, FZD9, GPC1, PAK1, FZD1, and ACTB were extracted." (PMID 30733969, 2019). "Previous studies suggest that iloprost binds with Fzd9 to induce anti-cancer signaling, however, prostacyclin may also generate effects by increasing Fzd9 expression." (PMID 27339092, 2016). "Subsequently, we focused on a group of six candidate genes (Cd74, Lpl, Ifi44, Sat1, Fzd9 and Wwc1) that have been reported to be frequently regulated by epigenetic mechanisms and participate in the regulation of important signal pathways during cancer development and progression." (PMID 34836197, 2021). "When FZD9 binds to Wnt7a in the lung epithelium and initiates anti-cancer signaling through PPARγ, it does not activate canonical β-catenin signaling." (PMID 35924166, 2022). "In this context, whereas previous results suggest that targeting Fzd9 may not be the best strategy for cancer therapy because of its dual pro- and anti-tumorigenic character, our data indicate that it might be at least a valuable target when up-regulated in Myc-driven malignancies." (PMID 33653688, 2021). "Therefore, FZD9 may not be the best target for cancer therapy due to its dual character." (PMID 29789460, 2018).
CNS tumor (1 paper, 2023). "In keeping herewith, we show through ChIP-seq data that components of the Wnt-pathway such as FZD2 and FZD9 are direct targets of PLAGL1 and PLAGL2 and are overexpressed in the PLAGL1/2-amplified samples compared to the other CNS tumor types." (PMID 36437415, 2023).
infection (1 paper, 2021). The state of being infected such as from the introduction of a foreign agent such as serum, vaccine, antigenic substance or organism. "Partial loss of Wnt pathway receptor Fzd5 or Fzd9 through RNA-mediated gene silencing significantly reduces infection, indicating activation of the pathway during infection occurs at the level of the receptor complex." (PMID 33883266, 2021).
FZD9 also shares sentences with these, for which no sentence is quoted: gastric cancer (2 papers); B-cell lymphomas (1); breast tumors (1); colorectal cancer (1); esophageal cancer (1); genetic disease (1); glioblastoma (1); gout (1); hepatoblastoma (1); Huntington disease (1); large cell carcinoma (1); ovarian carcinoma (1); pancreatic cancer (1); Parkinson disease (1); pituitary adenomas (1); prostate carcinoma (1); spinocerebellar ataxia (1); squamous cell carcinoma (1); T-cell lymphomas (1).